TERT (telomerase reverse transcriptase)
Diseases named in the same sentence as TERT in open-access papers (continued):
Sharing a sentence is not in itself a finding about the gene and the disease.
tumor (continued). "Cell viability assays and ED50 studies of growth inhibition confirmed that Ad-TERTp-E1A-1504 has 3.5- and 1,400-fold greater ability to kill EphA3- and TERT-expressing tumor cells compared to Ad-TERTp-E1A-NC and Ad-ΔE1A-1504, respectively." (PMID 25978371, 2015). "3D-CSC subsets from in vivo tumor of control group manifest synchronous expression of TERT, CD29, CD44, CD90, CD105, CD133 and MUC-1 for renewable potential under spheroid-flow immunofluorescence scan." (PMID 26512920, 2015). "Collectively, 5-AZA mediates the down-regulation of TERT expression, and induces telomere dysfunction, which consequently exerts an anti-tumor activity." (PMID 25682873, 2015). "This virus stimulated an antigen-specific CTL response against TERT in mice that was correlated with a clear anti-tumour effect." (PMID 26085010, 2015). "It is well-established that HBV and its encoded proteins greatly contribute to these processes by regulating the expression of multiple tumor-related genes, such as human telomerase reverse transcriptase (TERT), β-catenin, and Snail, etc20." (PMID 26593394, 2015). "When present in tumor cells the telomerase generated protein TERT is processed and presented through the HLA class I pathway and is capable of stimulating CD8+ T cells." (PMID 26807308, 2015). "Because tumor-specific oncolytic adenovirus can amplify many times in infected cancer cells and dissolve them, a TERT promoter driven CRAd was regarded to be the most widely targeting tumor (90% of tumor) and a more potent replicating CRAd." (PMID 25978371, 2015). "It was demonstrated that TERT protein expression level was increased in NPC tumor tissue and metastatic lymph nodes." (PMID 25435972, 2015). "To the best of our knowledge, we believe that the present report provides the first description of a combined tumour immunotherapy that targets both TERT and VEGFR-2." (PMID 26085010, 2015). "Western blot confirmed that Ad-TERTp-E1A-1504 and Ad-ΔE1-1504 significantly suppressed EphA3 and AKT, mTOR and 4-ebp1 phosphorylation compared with Ad-TERTp-E1A-NC and Ad-ΔE1-NC, respectively, in TERT- and EphA3-positive tumor cells." (PMID 25978371, 2015). "The ratio of cytoplasmic TERT/nuclear TERT for the primary tumor of the 6–10B cell line was almost six-fold higher than that of the metastatic lymph nodes of the 5–8F cell line." (PMID 25435972, 2015). "TERT also possess telomere independent functions in tumor formation and other human diseases, regulating Wnt-dependent transcription, mitochondrial function and apoptosis and DNA damage response." (PMID 26298771, 2015). "TERT is the transcriptional catalytic subunit for telomerase activity and is considered to have a critical role in tumor formation." (PMID 26298771, 2015). "Since the discovery of telomerase reactivation in cancer, many cis-regulatory elements and corresponding transcription factors have been suggested to contribute to the regulation of TERT in healthy cells and its aberrant expression in tumor cells." (PMID 26194807, 2015). "Ad-TERTp-E1A-1504 killed almost all TERT-positive tumor cells, C4-2B and HGC27 at 0.1–10 MOI at 3 days postinfection, but fewer TERT-negative cells were killed (2BS), even at 100 MOI." (PMID 25978371, 2015). "Regulation of telomerase reactivation in tumor cells is complex and multifactorial and involves direct transcriptional activation as well as epigenetic regulation of TERT mRNA expression." (PMID 26143636, 2015). "In summary, Ad-TERTp-E1A-1504 did not harm TERT-negative cells but was oncolytic and inhibited TERT- and EphA3-positive tumor cells, which was also validated in vivo." (PMID 25978371, 2015). "Analysis of plasma from 4 patients identified mutations identical to those found in tumor specimens (BRAF, NRAS, TERT)." (PMID 25516806, 2014). "The tumor specimens derived from 109 patients with RCC and 14 patients with UTUC were analyzed for TERT promoter mutations." (PMID 24742867, 2014).
tumor (continued). "While TR has broad tissue distribution and is constitutively present in normal and tumour cells, TERT is the rate-limiting component of the telomerase complex, and its expression generally well correlates with telomerase activity." (PMID 24572088, 2014). "TERT is essential for unlimited cell growth, and thus plays a critical role in tumor formation and progression." (PMID 24572088, 2014). "Cooperative regulation of miR-375 targets along with the increase of tumor suppressors led to ~60% reduction of telomerase reverse transcriptase (TERT) transcription followed by ~35% decrease of telomerase activity." (PMID 24708873, 2014). "Second, tumor samples contain a mixture of tumor and other cell types, such as immune and vascular endothelial cells among others, making it difficult to measure TERT expression levels in tumor cells exclusively." (PMID 24937153, 2014). "Next generation sequencing techniques have shown that HBV is preferably integrated in tumor cells in comparison to non-tumor infected hepatic tissue and its integration correlates with deregulated expression of TERT, MLL4 and CCNE cellular oncogenes." (PMID 25341666, 2014). "Tumor DNA derived from 220 patients with UTUC was analyzed for the TERT promoter status using Sanger sequencing." (PMID 25474136, 2014). "The high expression of TERT in tumor cells and the requirement of a sustained telomerase activity for their unlimited proliferation capability make telomerase a particularly attractive target for cancer therapy." (PMID 24572088, 2014). "CR significantly decreased tumor incidence in TERT transgenic (TgTERT) mice and extended their lifespan compared to wild-type (WT) controls under the same diet, indicating a synergy between TgTERT and CR in increasing mouse longevity." (PMID 23349740, 2013). "In particular, although TERT overexpressing mice presented a higher incidence of neoplasias than WT mice, the incidence of these neoplasias was reduced to a similar incidence than that of WT mice under CR." (PMID 23349740, 2013). "The association between the TERT rs2736098 polymorphism and NSCLC risk was further examined by stratifying the subjects according to tumor histology." (PMID 24260099, 2013). "Increased expression of TERT and telomerase activation has been demonstrated to be directly related to maintenance of cellular replicative immortality which is crucial for tumor progression." (PMID 23967300, 2013). "A more selective agent for the MYC G-quadruplex is the telomestatin derivative S2T1-6OTD, which has been shown to reduce the expression of MYC and TERT in childhood MB and in AT/RT tumor cells and has potent antiproliferative effects." (PMID 24152672, 2013). "The relationship between genotype and TERT expression was generally consistent between cancer tumour types." (PMID 24152305, 2013). "As proxies for telomerase activity in tumour tissue samples we investigated the expression of the catalytic subunit of telomerase (TERT) and one of the main components of shelterin, the TRF1-intercating nuclear factor 2 (TINF2)." (PMID 22952882, 2012). "We found that expression ratios of TERT gene in HCC tissues to the tumor-adjacent tissues were 18.7, 1.0, and 0.33 (median of 6) respectively." (PMID 23236287, 2012). "Upon reactivation of telomerase in tumor cells, TERT is processed and presented on the MHC class I molecules of tumor cells." (PMID 21798027, 2011). "Several tumor-inducing viruses have evolved strategies to evade or subvert mechanisms controlling cellular senescence, mainly via the up-regulation of TERT, which is generally the limiting factor for telomerase activity." (PMID 22046133, 2011). "This gene is active during the embryonic development and in tumor cells (in approximately 85% of all cases), whereas the expression of TERT is suppressed in the overwhelming majority of normal cells in the organism." (PMID 22649681, 2011).
tumor (continued). "With regard to NPC, increased telomerase activity and TERT expression is also common in tumor tissues, and can be detected at high frequencies compared with normal nasopharyngeal epithelium and tissues." (PMID 21929825, 2011). "Apparently, the mechanism of hTERTC27-induced tumor suppression in our study is different from that of peptides (p973, p988, p540) or TERT gene transfected DCs reported in other studies." (PMID 20856939, 2010). "Telomerase reverse transcriptase (TERT), the catalytic peptide subunit of telomerase, is expressed in more than 85% of human tumor cells but rarely in normal cells, making it an ideal target for antigen-specific cancer immunotherapy." (PMID 20856939, 2010). "In tumor-derived cells, TERT promotes tumor development, even if the cells possess telomeres of ample length." (PMID 18846223, 2008). "We conclude that HMECs transduced with ERα, BMI1, MYC and TERT readily form oestrogen-dependent tumours in mice." (PMID 17573968, 2007). "Most dramatically, in the five out of five informative tumours where we were able to amplify the TERT cSNP, expression appeared to be overwhelmingly from one parental allele." (PMID 16222316, 2005). "With TERT and Ab-2 polyclonal antibodies, nuclear staining was observed in tumour cells whereas activated lymphocytes and normal cells remained negative." (PMID 15026805, 2004). "While TERT promoter mutations and HBV DNA integration are both mechanisms for telomerase activation, studies suggest that they may co‐occur within the same tumor; however, some evidence indicates mutual exclusivity in certain contexts." (PMID 40833357, 2026). "Some studies suggest that β-catenin transcriptional activity may directly or indirectly influence TERT expression, further reinforcing the interplay between these pathways in tumor development." (PMID 40243493, 2025). "Notably, peripheral blood analysis from 389 patients showed a significant decrease in telomerase reverse transcriptase-positive (TERT +) leukocytes with tumor progression, a change detectable earlier than circulating tumor cells (CTCs)." (PMID 41417416, 2025). "TERC is an essential component of TERT's tumor promoting effect." (PMID 39871386, 2025). "The predictive value of TERT alterations was independent of tumor mutational burden and microsatellite status." (PMID 40365320, 2025). "Using proteomics, we showed that the NF2−/− tumours divided into two distinct groups with distinct underlying mutational spectrum, NF2 clusters 1 and 2, independent of NF2 severity score, chromosome loss, CDKN2A/B and TERT mutations." (PMID 40562609, 2025). "ASOs reversibly downregulate the level of TERT expression within hepatocellular carcinoma and cervical cancer, with the potential for additional specificity following conjugation using tumor-specific ligands." (PMID 39858038, 2025). "Indeed, we observed enhanced mtDNA replication in TERT-overexpressing cells, including both normal primary and tumor cells." (PMID 41144538, 2025). "Of the total TERT expression, the TERT-FL and TERT-β isoforms represented on average 17.7% and 67.9%, respectively, in 30 normal tissue types in GTEx, while 38.4% and 44.5%, respectively, in 33 tumor types in TCGA." (PMID 39956830, 2025). "In this context, targeting TERT’s extratelomeric functions could effectively suppress tumor proliferation and promote apoptosis." (PMID 40227701, 2025).
tumor (continued). "Tumor behavior linked to NF2, CDKN2A/B deletions, and TERT mutations may influence radiotherapy response." (PMID 39779595, 2025). "However, multivariate analysis showed only the aggressive tumour subtype, high AXL expression, and TERT promoter mutation were independently associated with RAI-refractory status." (PMID 40241101, 2025). "The tumor-specific telomerase reverse transcriptase (TERT) promoter drives simultaneous expression of tumor necrosis factor superfamily member 14 (LIGHT) and membrane-anchored anti-CD3 single-chain variable fragment (αCD3), which are important immunomodulators with closely clinical relevance." (PMID 41406950, 2025). "Despite these insights, none of the 16 studies included molecular or epigenetic tumor profiling, such as TERT promoter mutations, CDKN2A/B deletions, or methylation subclasses, which are increasingly shown to correlate with prognosis and RT responsiveness." (PMID 40940847, 2025). "When the expression of TERT was silenced with antisense oligonucleotides in human liver cancer cell lines and in xenograft mouse models, it led to proliferation arrest and death of tumor cells." (PMID 39915447, 2025). "The discovery of TERT’s extratelomeric functions in tumor growth and progression suggests that targeting these functions could offer therapeutic benefits beyond its direct effect on telomeres." (PMID 40227701, 2025). "In this study, univariate analysis revealed that 6 variables significantly increased the risk of RAI-refractory DTC: histopathological aggressive tumour subtype, TNM stage II and above, LVI presence, m-ETE, high AXL expression, and TERT promoter mutation (all p values < 0.05)." (PMID 40241101, 2025). "Moreover, in longitudinal monitoring of five patients, the TERT mutant allele frequency (MAF), i.e., the proportion of tumor-derived DNA among total detected cfDNA, decreased following resection and chemoradiation and increased upon tumor progression." (PMID 40285800, 2025). "Since somatic mutations in the TERT promoter and FGFR3 have been found in normal urothelium and are commonly reported in tumor tissues by The Cancer Genome Atlas (TCGA), they are considered potential driver mutations in the development of both low-grade and high-grade NMIBC." (PMID 40995307, 2025). "This suggests the possibility of telomere transfer between tumour and immune/other cells within the tumour microenvironment might alter TL, contributing to TERT activation." (PMID 41026782, 2025). "Unlike telomere-directed approaches, which may require prolonged treatment to achieve effective telomere erosion, inhibiting TERT’s extratelomeric functions offers the prospect of rapid tumor-specific effects." (PMID 40227701, 2025). "Comprehensive Sanger sequencing of the resected tumor tissue revealed no mutations in the TERT promoter or the BRAF V600E gene." (PMID 40013148, 2025). "Circulating tumor DNA (ctDNA) reflects the mutational landscape of tumor tissues and has been shown to reliably detect various HCC-related mutations, including those in TERT and CTNNB1 35,36." (PMID 40765562, 2025). "In 67% of the PDC and 100% of the ATC, TERT activation segregated with tumor dedifferentiation." (PMID 40272676, 2025). "The tumor specificity of the TERT rearrangement breakpoint may make it a better marker than a gene amplification, because the ALK copy-number gain plays against the normal diploid background of cfDNA derived from nonmalignant cells." (PMID 39760332, 2025). "In contrast, the TERT promoter variant C228T was not present in tumor 3 but was present in every other tumor (green tumor)." (PMID 40489430, 2025). "Although molecular profiling (e.g., CTNNB1 or TERT promoter mutations) was not available, the tumour's strong beta-catenin and Glypican-3 expression supported a diagnosis of HCC." (PMID 41583252, 2025).
tumor (continued). "Therefore, if a mutation in the TERT promoter is detected in an MLS, it can be concluded from the available data that this mutation is probably distributed throughout the entire tumor." (PMID 40489430, 2025). "We hypothesize that this fusion may lead to upregulated TERT expression and/or contribute to cytoskeletal remodeling, thereby enhancing tumor cell motility and increasing invasive potential." (PMID 40725486, 2025). "Univariable Cox regression analysis showed that patients with unifocal and multiple gliomas had five similar risk factors (age, tumor location, peritumoral edema, enhancement intensity, WHO grades) and four different risk factors (extent of resection, 1p19q/IDH/TERT status)." (PMID 40496616, 2025). "Moreover, the observation that TERT inhibition per se induces pro-apoptotic effects and sensitizes tumor cells to chemotherapeutic agents is promising." (PMID 40227701, 2025). "Telomerase activity is upregulated in many tumor types, including HNSCC, through various mechanisms including chromosomal rearrangements, amplification of TERT gene, and activating mutations in the regulatory region of TERT gene." (PMID 41487579, 2025). "TERT-β, which encodes a telomerase-nonfunctional protein, is the major TERT isoform in both normal and tumor tissues." (PMID 39802763, 2024). "In addition, PIK3CA and TERT gene mutations have also been detected in some RGNT cases, and these mutations are closely associated with the biological behavior of the tumor and the potential risk of malignant transformation." (PMID 39457636, 2024). "Further molecular analysis with the Oncomine Comprehensive Assay v3 (OCAv3) and ThyroSPEC revealed an ETV6::NTRK3 fusion-positive tumor harboring an additional TERT promoter mutation c.-124C>T, with no other genetic alterations." (PMID 38642578, 2024). "Previous studies have shown that Trx1 and TERT have anti-tumor synergistic effects." (PMID 38730567, 2024). "TERT mutations allow tumour cells to grow without restriction and are found in many types of tumours." (PMID 39530091, 2024). "Although many tumors protect against telomere crisis via transactivation of TERT as previously discussed, telomere shortening and fusion events have been seen in clonal tumor populations with TERT activity, suggesting breakage-fusion-bridge cycling is possible in such cancers." (PMID 39095874, 2024). "Furthermore, the authors successfully established a cell line containing the BRAFV600E mutation, TERT promoter mutation and CDKN2A/2B loss from recurrent tumour derived from an autopsy." (PMID 39107839, 2024). "Previously, AMPK activation was shown to be upstream to TERT transcription in tumor cells." (PMID 39456503, 2024). "Mutations in TERT (telomerase reverse transcriptase promoter) and ATRX may allow tumor cells to escape apoptosis." (PMID 38674026, 2024).